ACE (angiotensin I converting enzyme)
Diseases named in the same sentence as ACE in open-access papers (continued):
Sharing a sentence is not in itself a finding about the gene and the disease.
angioedema (continued). "Herein, we report a case of a morbidly obese patient who developed life-threatening airway obstruction due to angioedema in the postoperative period, which was probably mediated by an ACE inhibitor." (PMID 33398469, 2021). "As no specific laboratory test is available for the identification of AAE-ACEI, this disorder can be diagnosed only by excluding other types of bradykinin-mediated angioedema, when the complement tests are performed at the discontinuation of ACE inhibitors." (PMID 34956216, 2021). "We calculated information coefficients (ICs) by performing a disproportionality analysis to evaluate DPP-4/ACE inhibitor-induced angioedema using the Japanese Adverse Drug Event Report (JADER) database." (PMID 34884209, 2021). "Longitudinal observational research is needed to fully understand the association between ACE inhibitor/DPP-4 inhibitor use and vasoactive peptide-induced angioedema." (PMID 34884209, 2021). "In the present study, the frequency of ACE inhibitor-induced angioedema was 4.7%, which is higher than in the adult population." (PMID 34284535, 2021). "Of the patients treated with DPP-4 inhibitors, four developed drug-induced angioedema in combination with ACE inhibitors, and all were taking vildagliptin." (PMID 34884209, 2021). "This patient was found to have a latent deficiency of bradykinin-degrading enzymes, supporting the relevance of the simultaneous ACE and DPP-IV inhibition in subjects with risk factors for angioedema." (PMID 34872575, 2021). "A signal was detected (IC: 2.42, 95% CI: 2.19–2.65) in 176 cases of ACE inhibitor-induced angioedema." (PMID 34884209, 2021). "Of the reported cases of DPP-4 inhibitor-induced angioedema, four were in combination with an ACE inhibitor." (PMID 34884209, 2021). "Inhibition of kinin degradation by ACE/kininase II and also, in the case of omapatrilat, by neprylisin is involved in these drug-induced angioedemas." (PMID 33800422, 2021). "While 8 (8.6%) patients reported angioedema that was triggered by a medical treatment, 3 (3.3%) patients reported treatment with angiotensin converting enzyme (ACE) inhibitors during the last 12 months before enrollment." (PMID 33343800, 2020). "In other studies, greater side-effects related to ACE inhibitors have been reported for women, such as cough or angioedema." (PMID 32210137, 2020). "Icatibant is a bradykinin B2 receptor antagonist indicated for Hereditary Angioedema (HAE) types I and II and is used off-label for HAE with normal C1INH (HAE-nC1INH) and ACE-inhibitor induced angioedema (ACEIIAE)." (PMID 33292436, 2020). "Patients experiencing angioedema while using an ACE inhibitor must discontinue the medication and avoid all ACE inhibitors in the future." (PMID 31655853, 2020). "This occurs in hereditary and acquired angioedema (often associated with B-cell lymphoproliferative diseases), associated with deficiency or dysfunction of the C1 esterase inhibitor, or in angioedema induced by ACE inhibitors." (PMID 32390768, 2020). "Synthetic inhibitors of angiotensin-I converting enzyme (ACE) are the most used anti-hypertensive drugs; however, they can cause skin rashes, cough, angioedema, hypotension, renal disfunction, and other disturbing side effects." (PMID 31801290, 2019). "Food-derived ACE inhibitors such as peptides with high ACE inhibitory activity are believed safer than drugs with related side effects, such as cough and angioedema." (PMID 31487872, 2019). "Initial results were promising, however there was a higher occurrence of angioedema reported in patients on dual treatment compared to ACE inhibitor alone, therefore development was halted." (PMID 31072047, 2019). "Overall correct classification of the level of contraindication for intolerances was low ranging from 6.9% for statin induced rhabdomyolysis to 66.5% for angiotensin-converting-enzyme (ACE) induced angioedema where it was absolutely contraindicated." (PMID 30923609, 2019).
angioedema (continued). "ACE inhibitors have side effects of dry cough and angioedema related to the increase in bradykinin levels, and ACE inhibitors and ARBs inhibit the synthesis of aldosterone, resulting in side effects of hyperkalemia." (PMID 31262348, 2019). "Patient did not regain consciousness, despite full clinical resolution of ACE inhibitor induced angioedema." (PMID 30075570, 2018). "Because of the extremely high consumption of ACE inhibitors, angioedemas due to ACE inhibitors have become frequent in Germany." (PMID 31826031, 2018). "Angiotensin-converting enzyme (ACE) inhibitors and middle cerebral artery distribution have been associated with a higher risk of developing angioedema." (PMID 30363665, 2018). "The weighted incidence of angioedema with ACE inhibitors was 0.30% (95% CI 0.28% to 0.32%) compared to 0.11% (95% CI 0.09 to 0.13) with ARBs, 0.13% (95% CI 0.08% to 0.19%) with DRIs, and 0.07% with placebo (95% CI 0.05 to 0.09)." (PMID 29728119, 2018). "Overall, these clinical data support the following mechanism: tPA administration triggers bradykinin generation, which is itself able to promote angioedema, especially in patients taking ACE inhibitors." (PMID 30018956, 2018). "ACE inhibitors lead to recurrent angioedemas in approximately 0.1 – 2.2% of users; frequently, the face or the tongue are affected." (PMID 31826031, 2018). "In the case of HAE, AAE or ACE inhibitor-induced angioedema, the vasodilatory peptide, bradykinin, plays a key role in endothelial cell activation, with resultant tissue edema." (PMID 30263036, 2018). "Our case highlights the importance of educating clinicians and emergency specialists about ACE inhibitors induced angioedema, as a potentially fatal drug reaction." (PMID 30075570, 2018). "Considering the fact that no laboratory or confirmatory tests exist to diagnose ACE inhibitors induced angioedema, clinicians’ knowledge and experience is the key element in recognition of ACE inhibitors induced angioedema." (PMID 30075570, 2018). "Bradykinin is released from many cell types, and mechanisms that interfere in either its production—or as in the case of ACE inhibitors—its degradation, result in angioedema." (PMID 30263036, 2018). "ACE inhibitor-induced angioedema primarily occurs because of the enzymatic inhibition of bradykinin degradation." (PMID 30514395, 2018). "While ACE is the major kinin-destroying peptidase in the extracellular fluid, ACE inhibitor-induced angioedema is reportedly resistant to the plasma kallikrein inhibitor ecallantide and to the B2R antagonist icatibant." (PMID 30333824, 2018). "Death due to cardiopulmonary insufficiency occurred 24 days after the admission to intensive care unit, despite full clinical resolution of ACE inhibitor-induced angioedema." (PMID 30075570, 2018). "Our case highlight the importance of educating clinicians about ACE inhibitor-induced angioedema, as potentially fatal adverse drug reaction." (PMID 30075570, 2018). "For the patients that developed severe angioedema, odds ratios for severe angioedema development were calculated for ACE inhibitor use and comorbidities." (PMID 30363665, 2018). "Considering the fact, that no laboratory or confirmatory test exist to diagnose ACE inhibitor-induced angioedema, clinicians’ knowledge is the key element in recognition of ACE inhibitor-related angioedema." (PMID 30075570, 2018). "In regards to tPA-induced angioedema of all severities, previous studies have suggested an increased incidence in those with concomitant use of ACE inhibitors and with MCA territory distribution." (PMID 30363665, 2018). "Rare cases of angioedema following local trauma in patients using ACE inhibitors have been published." (PMID 28348897, 2017). "The patient received acetylsalicylic acid which has angioedema listed as extremely rare adverse effect, but the ACE-inhibitor was by far the most suspicious pharmaceutical on the list." (PMID 27123347, 2016).
angioedema (continued). "So the incidence of ACE inhibitor-induced angioedema in Caucasians amounted to 0.1–0.7%, whereas the susceptibility of colored Americans was much higher." (PMID 28025602, 2016). "The next morning the patient’s swelling had significantly improved and she was diagnosed with angioedema secondary to ACE inhibitors." (PMID 27833699, 2016). "Since its approval, meanwhile dozens of patients suffering from ACE inhibitor-induced angioedema were treated successfully off-label." (PMID 28025602, 2016). "This would mean a calculated incidence of 1:4,000, which means that ACE inhibitor-induced angioedema occurs much more frequently than HAE." (PMID 28025602, 2016). "It was unravelled that the patient 5 years ago was taking an ACE-inhibitor as an antihypertensive drug on a daily basis and thus bradykinin mediated angioedema was suspected." (PMID 27123347, 2016). "While the possibility of ACE inhibitor-induced permeability and/or angioedema due to elevated kinin levels has been raised, ACE inhibitors have nonetheless generated interest and shown promise for DR/DME treatment." (PMID 27618014, 2016). "Angiotensin-converting enzyme inhibitor (ACE-I) induced angioedema is a known side effect of ACE inhibitors." (PMID 27833699, 2016). "One characteristic of ACE inhibitor-induced angioedema is the regular manifestation in the area of the airways." (PMID 28025602, 2016). "The incidence of ACE inhibitor-induced angioedema varies according to the different examinations, probably because of ethnical differences." (PMID 28025602, 2016). "During clinical trials of NEP inhibitors, up to 2.17 % of patients and 0.2–0.65 % of patients prescribed ACE inhibitors developed angioedema." (PMID 27122021, 2016). "Among the nearly 7 million patients treated with ACE inhibitors in Germany and an assumed rate of angioedema of 0.3–0.5%, around 20,000-35,000 cases have to be expected annually." (PMID 28025602, 2016). "ACE inhibitor-induced angioedema is thought to be mediated by decreased bradykinin breakdown resulting in increased bradykinin levels." (PMID 25140014, 2015). "After discontinuation of the ACE inhibitor, 46% of patients had further recurrences of angioedema, although less-frequent." (PMID 25664168, 2015). "ACE inhibitor intake withdrawn is the main treatment and the only prophylactic measure to avoid the drug-induced angioedema." (PMID 25431681, 2014). "Although it is rare, cases of central nervous system involvement have been reported in patients with HAE and ACE inhibitor-induced angioedema." (PMID 24792779, 2014). "The probability that a patient taking an ACE inhibitor will go on to develop angioedema is 0.1–0.7%." (PMID 25431681, 2014). "For example, the estimated incidence of angiotensin-converting enzyme (ACE) inhibitor-induced angioedema is 0.1 to 1.0 % and that of hereditary angioedema (HAE) ranges from 0.002 to 0.01 %." (PMID 24792779, 2014). "Given the estimated incidence of ACE inhibitor-induced angioedema of 0.1 to 1.0 % and the large number of patients on ACE inhibitors, one theory is that affected individuals have an underlying partial deficiency of C-1 esterase." (PMID 24792779, 2014). "Patients should avoid known triggers of angioedema such as exogenous estrogen and angiotensin converting enzyme (ACE) inhibitors." (PMID 25352908, 2014). "Although, there are reports that 10% of patients with previous ACE inhibitors angioedema also develop this adverse reaction after changing the medication to ARBs." (PMID 25431681, 2014). "Whenever possible, avoiding airway manipulating should be one of the angioedema preventive anesthetic attitudes for patients taking ACE inhibitor." (PMID 25431681, 2014). "Angiotensin-converting enzyme (ACE) inhibitors are widely prescribed and are the leading cause of a drug-induced angioedema." (PMID 25431681, 2014).
angioedema (continued). "We conclude that the patient had a severe life-threatening angioedema with high probability that the etiology was directly related to the previous treatment with an ACE inhibitor." (PMID 25431681, 2014). "Glossomegaly (swelling of the tongue) is a common finding of angioedema, with isolated glossomegaly reportedly more common in patients with ACE inhibitor-induced angioedema than HAE." (PMID 24792779, 2014). "The main difference in side effects is the relatively high incidence of angioedema with the use of ACE inhibitors in patients of African ancestry." (PMID 23721258, 2013). "The lisinopril was stopped, the patient commenced on alternative anti-hypertensive medication and the angioedema resolved, consistent with a diagnosis of ACE inhibitor sensitivity." (PMID 22340023, 2012). "ARBs have superior tolerability over ACE inhibitors, which inhibit the degradation of bradykinin, leading to adverse effects, such as dry cough and angioedema." (PMID 22490507, 2012). "Serum ACE also catabolises Bradykinin (BK) which influences the manifestation of angioedema in allergic disease." (PMID 23316249, 2012). "Our study demonstrates a link between ACE genotype and anaphylaxis to food, venom, and drugs, particularly for reactions that include cardiovascular collapse and severe angioedema." (PMID 23316249, 2012). "The ACE inhibitors account for 20% to 30% of all angioedema cases presenting to emergency departments." (PMID 23304594, 2012). "The mechanism of angioedema induced by angiotensin converting enzyme inhibitors (ACE inhibitors) is a class effect that is directly related to the mechanism of action." (PMID 23304594, 2012). "Acquired angioedema includes, among other etiologies, ACE inhibitor-induced angioedema and angioedema due to acquired C1-inhibitor deficiency." (PMID 23282382, 2012). "One report described a patient with ACE inhibitor-induced angioedema whose bradykinin levels rose acutely during the episode and normalized after it." (PMID 23304594, 2012). "Angiotensin converting enzyme (ACE) inhibitor sensitivity: 0.5% of patients were diagnosed with angioedema secondary to an angiotensin converting enzyme (ACE) inhibitor." (PMID 22340023, 2012). "ACE inhibitor-induced angioedema can be life-threatening when it involves the upper airway and, therefore, ACE inhibitors should be discontinued in all individuals with angioedema." (PMID 22165855, 2011). "ACE-inhibitor-induced angioedema should be considered if complement studies are normal and the patients is currently using ACE inhibitor therapy." (PMID 22165855, 2011). "In this analysis, 90 incident angioedema-related events were reported, of which 31 occurred in patients while on an ACE inhibitor." (PMID 20412573, 2010). "The onset of angioedema is variable; it can occur within the first 24 hours of ACE inhibitors use, however weeks, months and years have also been described." (PMID 20180980, 2010). "The most common locations for angioedema-ACE inhibitors induced are lips, tongue, oropharinge, and larynge." (PMID 20180980, 2010). "Some consider its use contra-indicated, but only a small percentage of patients with ACE inhibitor-related angioedema continue with this symptom when switched to an angiotensin II receptor blocker." (PMID 20180980, 2010). "Some authors attribute the ACE-inhibitor-related angioedema to the increased levels of bradykinin and substance P." (PMID 20180980, 2010). "In patients who have experienced ACE inhibitor-related angioedema, ARB should be used cautiously used." (PMID 20180980, 2010). "In patients who have experienced ACE inhibitor-related angioedema, angiotensin receptor blockers should be used cautiously." (PMID 20180980, 2010). "ACE inhibitors-induced angioedema is uncommon and the clinical presentation is variable with lips, tongue, oropharinge, and larynge as the most common locations." (PMID 20180980, 2010).
angioedema (continued). "About 50% of patients with ACE inhibitor-induced angioedema occur within the first week of treatment." (PMID 23282406, 2008). "The number of incident angioedema-related events per 100 patient-years while a patient was on an ACE inhibitor was the same (0.9) in both groups." (PMID 18954434, 2008). "Among the 6139 patients included in this pooled analysis, there were 54 incident angioedema-related events, 16 of which occurred in patients concurrently taking an ACE inhibitor." (PMID 18954434, 2008). "In both groups, angioedema were reported (26% and 21% of those patients who discontinued ACE inhibitors)." (PMID 17052329, 2006). "Angiotensin-converting enzyme (ACE) inhibitor-induced angioedema is a rare but potentially life-threatening adverse effect that may occur years after treatment initiation." (PMID 41658732, 2026). "Additionally, angiotensin converting enzyme (ACE) inhibitors are another group of drugs that can induce angioedema." (PMID 40599632, 2025). "This case reaffirms the importance of early recognition of ACE inhibitor-induced angioedema." (PMID 41035577, 2025). "A rarer pathophysiological mechanism of AE is bradykinin-mediated angioedema (AE-BK), which results from excessive bradykinin production due to dysregulation of the contact pathway, or decreased catabolism, such as in ACE inhibitor-induced AE, leading to edema." (PMID 40004905, 2025). "Glucocorticoids induce ACE expression and are thus expected to increase bradykinin metabolism, which may theoretically alleviate bradykinin-induced angioedema." (PMID 40013202, 2025). "However, increasing evidence suggests that elevated levels of angiotensin II can indirectly inhibit ACE activity, thus potentially triggering angioedema, even in patients taking ARBs." (PMID 40636633, 2025). "Importantly, if the angioedema is induced by ACE inhibitors or ARBs, discontinuation of the offending drug is crucial." (PMID 40636633, 2025). "Additionally, AE can result from various medications (e.g., ACE inhibitors, hormones, NSAIDs, etc.), leading to what is termed drug-induced angioedema (AE-DI)." (PMID 40004905, 2025). "ACE inhibitor-induced angioedema typically impacts the lips, tongue, face, and upper airway." (PMID 38543146, 2024). "In addition, during an episode of angioedema due to the use of the ACE inhibitor captopril, case reports showed a 10-fold increase in bradykinin levels, returning to normal levels during remission." (PMID 38543146, 2024). "Additionally, about half of patients experiencing ACE inhibitor-induced angioedema also have an enzyme defect involved in des-Arg9-BK metabolism, leading to its accumulation when ACE is inhibited." (PMID 38543146, 2024). "One of the most dangerous complications of ACE inhibitor therapy is angioedema, and pDDIs may trigger this life-threatening condition." (PMID 39124556, 2024). "Similarly, the ONTARGET study documented an overall occurrence rate of ACE inhibitor related angioedema at 0.3% among a population of 8,576 subjects." (PMID 38205154, 2024). "The diagnosis of ACE inhibitor-induced angioedema relies primarily on clinical suspicion." (PMID 38543146, 2024). "Infection with SARS-CoV-2 may give rise to a synergistic effect that leads to angioedema in patients receiving ACE inhibitors." (PMID 38910667, 2024). "African Americans may be at particular risk of developing angioedema with concomitant SARS-CoV-2 infection and ACE inhibitor use." (PMID 38910667, 2024). "ACE inhibitor-induced angioedema is a rare complication in patients receiving ACE inhibitors." (PMID 38910667, 2024). "For example, another study indicated that ARBs might be more cost-effective in certain subgroups of patients, particularly those intolerant to ACE inhibitors due to adverse effects like cough or angioedema." (PMID 39252272, 2024).